ERBB2 (erb-b2 receptor tyrosine kinase 2)
Diseases named in the same sentence as ERBB2 in open-access papers (continued):
Sharing a sentence is not in itself a finding about the gene and the disease.
breast cancer (continued). "This tumour model is particularly suited to studying the effects of 17-AAG since the tumours that arise are driven by the activated form of the NEU/HER2 oncogene and are addicted to it, just as ERBB2 amplified breast cancers in the clinic are driven by and addicted to the amplified ERBB2." (PMID 22621282, 2012). "Furthermore, we show that, across a wide array of breast cancer cell lines, PADI2 is specifically overexpressed in the luminal subtype, while also being highly correlated with HER2/ERBB2 overexpression." (PMID 23110523, 2012). "When all patients with locally advanced breast cancer were stratified, regardless of chemotherapy regimen (FEC vs FEC-T), both classifications for assessing ER/ESR1 and HER2/ERBB2 status were significantly associated with outcome." (PMID 23035882, 2012). "Taken together, these data suggest that in breast cancer cell lines with low/absent PTPN13 expression, and high ErbB2 expression, EphrinB1 phosphorylation is elevated as is its association with ErbB2 and correlates with enhanced Erk1/2 phosphorylation." (PMID 22279592, 2012). "This is the first study to describe a novel complex between ErbB2 and EphrinB1 that is not restricted to breast cancer cell lines but is present in many epithelial cell lines tested." (PMID 22279592, 2012). "Triple negative (TN) breast cancers are defined by lack of expression of estrogen, progesterone, and HER-2 (ERBB2) receptors." (PMID 22984505, 2012). "To assess the significance of the ErbB2/EphrinB1 interaction in breast cancer, we further analyzed: BT474, a Her2 (ErbB2) cell line; T47D, a luminal cell line with high ErbB2 expression; MCF7, another luminal cell line with low ErbB2 expression." (PMID 22279592, 2012). "Triple-negative breast cancer (TNBC) is an aggressive type of breast cancer that is clinically defined as lacking estrogen and progesterone receptors, as well as being ERBB2 (HER-2) negative." (PMID 22295252, 2012). "We investigated the influence of miR-125b on HER2 signaling pathway in ERBB2-negative breast cancer cell lines MCF-7." (PMID 22693547, 2012). "However wild-type KRAS is significantly activated in breast cancers that over-express EGFR and ErbB2." (PMID 22701724, 2012). "In the breast cancer cell lines studied, low/absent PTPN13 together with elevated ErbB2 expression correlate with enhanced ErbB2/EphrinB1 association as well as increased EphrinB1 and Erk1/2 phosphorylation." (PMID 22279592, 2012). "Given the previous correlations between PADI2 and the HER2/ERBB2 oncogene, the goal of this study was to carry out an initial test of the hypothesis that PADI2 plays a role in breast cancer progression." (PMID 23110523, 2012). "Similar to the breast cancer case, or even in PC, it may exist a connection between the over-expression of the HER2/neu (also known as ErbB2) and the progression to castrate resistant disease." (PMID 23133437, 2012). "Although trastuzumab as single agent has been proved active and well tolerated in treatment of breast cancer with ErbB2 overexpression, many tumors overexpressing ErbB2 do not respond to trastuzumab monotherapy, and acquired resistance does often develop." (PMID 24281706, 2012). "Alternative but not mutually exclusive mechanisms recently reported include disruption of Stat5a/b phosphorylation during breast cancer progression through upregulation of the Jak2 tyrosine phosphatase, PTP1B, or inhibitory signaling to Stat5 by the truncated ERBB2 isoform, p100-t-ERBB2." (PMID 23036105, 2012). "The involvement of the ErbB signaling pathway is not surprising – it is well-known that the ErbB protein family or epidermal growth factor receptor (EGFR) family, especially ErbB-2 (HER-2), is often over-expressed with aggressive clinical behavior and poor outcome in patients with breast cancer." (PMID 22346740, 2012). "BL breast cancers do not express the estrogen or progesterone receptors nor do they over-express ErbB2." (PMID 22279592, 2012).
breast cancer (continued). "Several of the fused genes are also recurrently broken in a substantial proportion of breast cancers, as judged by copy number steps in array-CGH of 1000 breast tumours: around 10% have breaks in ERBB2, BCAS3 and SKAP1, while COL14A1, TIAM1, USP32, TAOK1 are broken in around 4%." (PMID 23260012, 2012). "Together, these results suggest that PADI2 may function as an important new biomarker for HER2/ERBB2+ tumors and that Cl-amidine represents a new candidate for breast cancer therapy." (PMID 23110523, 2012). "Pak1 was shown to be activated in breast cancer cells that come from ER negative tumors that overexpress the ErbB2 oncogene." (PMID 23326684, 2012). "It has recently been proposed that a three-gene model (SCMGENE) that measures ESR1, ERBB2, and AURKA identifies the major breast cancer intrinsic subtypes and provides robust discrimination for clinical use in a manner very similar to a 50-gene subtype predictor (PAM50)." (PMID 22752290, 2012). "Also, ERBB2 RNA overexpression was demonstrated in 15–25% of HBC cases, and in 55% of cat mammary tumors." (PMID 22489125, 2012). "The late gene network is centered on ERBB2, a member of the epidermal growth factor (EGF) family of receptor tyrosine kinases, and one of the major molecular prognostic and predictive markers in breast cancer." (PMID 21878096, 2011). "In addition, suppression of v-erb-b2 erythroblastic leukemia viral oncogene homolog 2 (ERBB2) and ERBB3 by enforced expression of miR-125a or miR-125b resulted in impaired anchorage-dependent growth in breast cancer cells." (PMID 21394831, 2011). "This property of AST1306 is consistent with that of lapatinib that its activity is not dependent on EGFR expression level in ErbB2-overexpressing breast cancer cells." (PMID 21789172, 2011). "Preliminary data obtained in our pilot study (not shown) indicate that the TNFAIP1/POLDIP2 SFGM demonstrates stronger correlation pattern not with the ERBB2 breast cancer subtype but rather with luminal A and B subtypes." (PMID 20158880, 2010). "In both ER-and ER+ breast cancer we observed a strong correlation between the ERBB2, RAS and AKT pathways (Pearson correlation between RAS and AKT was 0.61 in ER+ and 0.59 in ER-), consistent with AKT-signalling a direct downstream target of RAS and ERBB2." (PMID 21050467, 2010). "Importantly, patient survival was significantly reduced in breast cancers where MYC and ErbB2 are co-amplified." (PMID 20840765, 2010). "For example, ER mRNA and protein can be downregulated in MCF-7 cells by stably overexpressing EGFR or constitutively activating erbB-2, Raf, or MEK; and in a number of ER- breast cancers, ER expression can be restored by inhibiting GFR through targeting of MAPK/ERK." (PMID 20569503, 2010). "Furthermore, our data, supported by subtype classifications of independent breast cancer data sets, indicate that the ERBB2 subgroup, although dominated by HER2+/ER- tumors, contains a sizeable fraction of HER2+/ER+ tumors." (PMID 20459607, 2010). "On the contrary, trastuzumab did not affect the level of ErbB2, differently from previous reports on sensitive mammary tumours." (PMID 20051960, 2010). "Despite the apparent similarity in the prevalence of ErbB2-positive breast cancer in Asian and Western countries, many Asian patients will not have the same opportunity as Western patients to receive ErbB2-targeted treatment." (PMID 20715159, 2010). "For instance, the levels of MiR-206 have been found to be higher in ERalpha-negative MB-MDA-231 cells than in ERalpha-positive MCF-7 cells, and enforced expression of miR-125a or miR-125b leads to coordinate suppression of ERBB2 and ERBB3 in the human breast cancer cell line SKBR3." (PMID 21192833, 2010).
breast cancer (continued). "We found that the risk of developing a visceral metastasis as the site of the first recurrence was significantly higher in women with triple negative and ERBB2+ breast cancers than in women with HR+/ERBB2- tumors." (PMID 19778431, 2009). "The differential gene expression patterns generated by microarray technology broadly classified breast cancer into two sub types ER positive (ER+/ErbB-2−) and ER negative (ER−/ErbB-2+)." (PMID 21556249, 2009). "NOTCH3 over-expression also has been shown to play a major role in the proliferation of ERBB2-negative breast cancer cells." (PMID 20040092, 2009). "Neither ERBB2 nor hCAP18 transcription levels in breast cancer patients correlated with relapse or mortality after 5 to 10 years of follow-up (data not shown)." (PMID 19183447, 2009). "This is illustrated by the case of a 59 yo postmenopausal female with ER/PR positive, ERBB2 negative breast cancer with biopsy confirmed metastasis to the left ischium and right adrenal gland." (PMID 19366446, 2009). "Until now, targeted therapeutics are only available for ER- and ERBB2-positive breast cancer, and no tailored therapy exists for triple-negative breast cancer." (PMID 19904273, 2009). "When ERBB2-negative breast cancer cells like MDA-MB-231 were involved, only palmitate, but not oleate, was shown to induce apoptosis." (PMID 19298655, 2009). "In this study, we document that in ErbB2-positive invasive breast cancer cells FA disassembly is rapid compared with ErbB2 negative cells where FAs are more stable and prominent at the cell periphery." (PMID 19190626, 2009). "Inhibition of PPARγ transcriptional activity using the antagonist GW9662 resulted in increased cell death, specifically of the ERBB2-positive BT474 and MDA-MB-361 breast cancer cells, in a time-dependent and dosage-dependent manner, but not of the ERBB2-negative MCF-7 or normal HMECs." (PMID 19298655, 2009). "This conclusion is supported by the observation that persistent ERK1/2 activation is found in a wide range of patient-derived mammary tumor cell lines, many of which do not harbor amplified expression of ErbB2 and the sequencing of breast cancer tumor genomes." (PMID 19457236, 2009). "Consistent with such a mechanism is the fact that both pertuzumab, which inhibits ErbB2/ErbB3 heterodimerization and signalling, and ALM are active preclinically against breast cancer cells that are not gene-amplified for ErbB2." (PMID 18841159, 2008). "In addition to ERBB2, EGFR is overexpressed in basal-like breast cancer and is a possible target for new anti-breast cancer reagents." (PMID 19007432, 2008). "Both Trastuzumab and Rapamycin are clearly effective inhibitors of ErbB2-mediated signaling; however, they do not block breast cancer cell growth in vitro or in vivo completely but rather attenuate cancer cell growth." (PMID 19077306, 2008). "These drugs do not inhibit expression of the ErbB2 transgene, as seen in both E18-14C-27 cells, which were derived from a tumor from these mice, and mammary tumors treated with CDDO-Me, 268, or the combination." (PMID 18628471, 2008). "In the present study, ERBB2 expression was also associated with combined high levels of AP-2α and its partner YY1 both in primary breast tumors, markedly in the absence of ERBB2 gene amplification, and in a breast cancer cell line." (PMID 18218085, 2008). "ERBB2 (HER2) and EGFR (ERBB1, HER1) are growth factor receptors (GFRs), members of the transmembrane receptor tyrosine kinase family, and are overexpressed in 25–30% and 7–20% of breast cancers, respectively." (PMID 19007432, 2008). "In summary, we found that Pin1-inhibition sensitized Her2-positive breast cancer cells to the mTOR-inhibitor Rapamycin, but not to the direct erbB2 inhibitor Trastuzumab." (PMID 19077306, 2008). "However, the minimum region of recurrent amplification within the 17q12 amplicon includes just the STARD3, ERBB2 and GRB7 genes in human breast cancer." (PMID 19424485, 2008).
breast cancer (continued). "Amplification of the ERBB2 (Her-2/neu) oncogene, which occurs in approximately 25% of breast carcinomas, is a known negative prognostic factor." (PMID 18702822, 2008). "For ErbB2 status, however, it was found that 43 miRNAs were significantly higher in ErbB2-negative as compared to ErbB2-positive breast cancers." (PMID 16784538, 2006). "However, a recent study demonstrated that ErbB2 increases the synthesis of the vascular endothelial growth factor (VEGF) protein via the activation of mTOR and p70S6K in human breast cancer cells." (PMID 16984645, 2006). "The results indicate that common variation in the ATM, CHEK2 or ERBB2 genes does not have a role in breast cancer aetiology or progression." (PMID 17132159, 2006). "The ataxia-telangiectasia mutated (ATM; MIM 607585), checkpoint kinase 2 (CHEK2; MIM 604373) and v-erb-b2 avian erythroblastic leukemia viral oncogene homolog 2 (ERBB2; also named HER2; MIM 164870) genes have been suggested to have an important role in breast cancer aetiology." (PMID 17132159, 2006). "EGFR/ERBB1 is overexpressed in 35% to 60% of breast cancers, which correlates with a negative steroid receptor status, increased ERBB2 and VEGF (Vascular endothelial growth factor) expression." (PMID 16168117, 2005). "Furthermore, high expression of FAK in breast cancer is related to activation of AKT and to the overexpression of receptor molecules such as ErbB2/Her2 and EGFR." (PMID 16288304, 2005). "Several of these regions contain genes known to be amplified in breast cancer, including ERBB2, EGFR and MYC, while others include genes not previously implicated in breast cancer, including PTK2." (PMID 16457699, 2005). "In view of these complexities, it is not surprising that erbB2 aberrant breast cancers have shown variable responses to anti-erbB2 therapeutics." (PMID 16168116, 2005). "For example, when tested in protein synthesis inhibition assays, scFv(FRP5)-ETA displayed an IC50 value towards SKBR3 breast carcinoma cells of 29 ng/ml, compared with a value of 32 ng/ml for e23(Fv)PE40, an ErbB2-specific molecule employing a scFv antibody fragment of e23 for cell targeting." (PMID 16168106, 2005). "In one study, the sensitivity of a panel of human breast cancer and other epithelial tumour cell lines to gefitinib was found not to be dependent on overexpression of EGFR, and was also suggested to be related to erbB2 expression." (PMID 15083203, 2004). "Our results thus suggest that the AP-2 is not involved in ERBB2 overexpression in the non-breast cancer cell lines we tested." (PMID 12942124, 2003). "We and others have shown that mRNA stabilisation is not responsible for ERBB2 overexpression in breast cancer cells." (PMID 12942124, 2003). "To determine the relationship between breast cancer progression and gene amplification, we screened 62 distant metastases and 122 primary breast tumours for the amplification of the proto-oncogenes MYC and ERBB2 and the 11q13 chromosomal region." (PMID 9310246, 1997). "There was no specific effect of erbB-2 antisense oligonucleotides on breast cancer cell lines that had no amplification of erbB-2." (PMID 7947086, 1994). "Racial disparities are particularly pronounced in estrogen receptor-positive/ERBB2-negative (ER + /HER2-) breast cancer, where Black patients treated with adjuvant chemotherapy experience worse outcomes than their White counterparts, a pattern that is less evident in ER- disease." (PMID 41495055, 2026).
breast cancer (continued). "NRG1 is up-regulated in several types of cancer including breast cancer, lung cancer, pancreatic cancer, and over-expression of NRG1 may activate downstream signaling pathways such as ERBB3/ERBB2 pathway, leading to the stimulation on cancer cell proliferation, invasion, and drug resistance." (PMID 40959099, 2025). "Depending on the presence or absence of target molecules such as androgen receptors, PGRMC1, and the PI3K/AKT/mTOR pathway, breast cancer is most commonly classified into three categories: estrogen receptor (ER)-positive/ERBB2-positive, ERBB2-negative, and triple-negative breast cancer." (PMID 40703556, 2025). "Therefore, the primary focus of breast cancer research has been on ERBB2 amplification and HER2 overexpression rather than mutations, and there are no standard therapies targeting ERBB2 mutations in breast cancer." (PMID 41154672, 2025). "Although 80% (1,252/1,565) of ERBB2mut breast cancer is non-amplified, the approval of T-DXd for hormone receptor–positive HER2-low/-ultralow cancers may modulate the added clinical value of identifying ERBB2 mutations in this cancer type context." (PMID 40178042, 2025). "Since 2018, the TAILORx and RxPONDER trials have demonstrated that the 21-gene recurrence score (RS) can be indicative of the benefit of adjuvant chemotherapy in hormone receptor (HR)–positive, ERBB2 (formerly HER2)–negative breast cancer with 3 or fewer positive lymph nodes." (PMID 41632146, 2025). "In a different study, miR-218-5p was found to have supported the ERBB2 and EGFR expression by inhibiting the LRIG1 in breast cancer cells, which shows that miR-218-5p, and LRIG1can act as an oncogene in breast cancer and can be used as a therapeutic target for breast cancer treatments." (PMID 38954213, 2025). "Additionally, a significant downregulation of PHLDA1 in primary human breast cancer was found by immunohistochemical staining and PHLDA1 was significantly less expressed in ErbB2-negative tumors as compared with ErbB2-positive tumors, where PHLDA1 was expressed abundantly." (PMID 39630301, 2025). "The same effect is present in breast cancer cells overexpressing the circular RNA circCDYL2, which stabilizes GRB7 (growth factor receptor-bound protein 7), an adaptor protein involved in the signaling pathways mediated by HER2 (receptor tyrosine-protein kinase erbB-2) expression." (PMID 40283927, 2025). "We demonstrate that ErbB2 levels determine the relative contributions of CDK4-cyclin D1 and c-Myc pathways, with distinct temporal dynamics and reversibility patterns that have not been previously characterized in the context of ErbB2 heterogeneity within luminal A breast cancer." (PMID 41161384, 2025). "Here, we evaluate pragmatic clinical outcomes among a cohort of younger low-risk patients with low ODX RS (ages 50 to 69 years with T1N0, hormone receptor–positive, ERBB2 [formerly HER2]-negative breast cancer and ODX RS 18) who received various permutations of adjuvant RT and ET." (PMID 40960828, 2025). "The study indicated that marked AT1R-overexpression defines a subpopulation of estrogen receptor-positive, ERBB2-negative breast cancer that may benefit from targeted therapy with ARBs, most particularly losartan." (PMID 38441940, 2024). "Intriguingly, the role of ITGB1 differed in various BC gene-editing models, with total blocking occurring in the PyVmT-induced mammary tumor model as opposed to ITGB1 knock-down in ErbB2 tumors that failed to stop breast carcinogenesis and only delayed it by 30 days." (PMID 38279122, 2024). "For instance, clinical trials have utilized non-humanized gallium-68 (68Ga)-labeled anti-erBB-2 (HER2) nanoparticles for positron emission tomography (PET) diagnosis of breast cancer, thereby presenting a challenge in the context of humanized nanoparticle application." (PMID 39220130, 2024).